SLC6A3 (solute carrier family 6 member 3)
Diseases named in the same sentence as SLC6A3 in open-access papers (continued):
Sharing a sentence is not in itself a finding about the gene and the disease.
cancer (14 papers, 2009 to 2025). A tumor composed of atypical neoplastic, often pleomorphic cells that invade other tissues. "It was found that the polymorphisms of SLC6A3 was highly associated with body mass index, which the later one have been strongly suggested as risk factor of many types of cancer including lung." (PMID 31641374, 2019). "Benztropine and GBR-12935 directly targeted the dopamine transporter DAT/SLC6A3, whose genetic alterations such as amplification were correlated with poor prognosis for cancer patients." (PMID 32102440, 2020). "Nevertheless, our study indicates that amplified SLC6A3/DAT in tumor cells is a promising novel target in cancer research and treatment." (PMID 32102440, 2020). "Our study also indicates that the frequent, genetic amplification of SLC6A3/DAT is targetable in cancers." (PMID 32102440, 2020). "In addition, a series of genetic variants in MICA, MICB, NFKBIL1, SLC6A3, CLPTM1L, and TERT have been found to be associated with the susceptibility and prognosis of different cancer types." (PMID 35003220, 2021). "SLC6A3 possible role in cancer might be due to the well-known protective effects of dopamine in tumours." (PMID 32599859, 2020). "Thus, amplified, overexpressed SLC6A3/DAT could be a novel promising target in cancer research and treatment." (PMID 32102440, 2020). "Results showed that GABRA3, SLC6A3, GABRQ, SCN4A, and GABRG3 were overexpressed in cancer compared with normal liver tissues." (PMID 35401884, 2022). "Cancer cases with DAT/SLC6A3 alteration(s) were significantly correlated with a poorer prognosis of cancer patients as compared to the no alteration group, as shown by the overall survival Kaplan-Meier estimate." (PMID 32102440, 2020). "Therefore, based on these results, we suggested that GABRA3, SLC6A3, GABRQ, and SCN4A might be cancer-specific targets of Carvacrol which were further screened in the subsequent study." (PMID 35401884, 2022). "Results showed that expressions of DRD1, GABRA3, SLC6A3, GABRQ, and SCN4A in cancer were significantly higher than those in noncancer tissues." (PMID 35401884, 2022).
tumor (14 papers, 2014 to 2023). "Seven tumor antigens (ADA, FYN, HDC, NFKBIZ, RASSF4, SLC6A3, and UPP1) associated with inferior prognoses and higher-level infiltration of antigen-presenting cells in PRAD were identified, thus promising candidates for mRNA vaccine." (PMID 35547260, 2022). "In summary, our work was focused on the methylation and expression analyses of GRIA4, VIPR2, SPOCK1 and SLC6A3, belonging to gene families involved in the crosstalk between tumour cells and the environment." (PMID 32599859, 2020). "Of note, in our experimental study SLC6A3 revealed the greatest average expression difference between tumour and normal tissues." (PMID 32599859, 2020). "In disagreement with our experimental data, SLC6A3 expression analysis revealed higher levels in tumours and SPOCK1 presented similar expression levels in both tissues." (PMID 32599859, 2020). "SPOCK1, SLC6A3 and GluR4 were significantly low-expressed in tumour respect to normal tissues, following the same pattern of the mRNA expression level." (PMID 32599859, 2020). "We observed a distinct increase of SLC6A3 mRNA (>200-fold) in ccRCC tissue compared to the normal parenchyma indicating a role as tumor suppressor gene." (PMID 26831905, 2016). "The more detailed histological analysis demonstrated that especially the proximal tubules expressed SLC6A3 at high levels, whereas its levels were moderate in the tumor." (PMID 26831905, 2016). "Further, we examined the promoter methylation levels of DELMRGs and found that several genes (such as OAS2, KALRN, SLC16A7, PER2) had significantly lower methylation levels in tumor samples, while several genes (SLC6A3, CDO1, and SERPINC1) were significantly higher methylated." (PMID 37795453, 2023). "SLC6A3 was strongly expressed at the membrane of tumor and normal cells, but also in the cytoplasm." (PMID 26831905, 2016). "Out of the identified regulators, six genes (SLC6A3, MITD1, CCS, LIPT2, ATOX1, and GLS) showed increased expression in tumor tissues, while PDHB had higher expression in normal tissues." (PMID 38159255, 2023). "Specifically, the expression levels of SLC6A3, MITD1, and PDHA1 exhibited an increasing trend with tumor pathological stage, whereas CCS, LIPT2, PDHB, and PDHA1 displayed a decreasing trend in response to radiation therapy." (PMID 38159255, 2023). "Thus, Benz could directly target SLC6A3/DAT on tumor cells independently of the dopamine uptake." (PMID 32102440, 2020). "In contradiction to the mRNA expression, SLC6A3 and NDUF4AL2 levels were lower in tumor compared to normal renal tissues." (PMID 26831905, 2016). "The genes expression levels in the model were detected by qRT-PCR, and the results showed that they were highly expressed in 20 pairs of tumor and normal tissues (UNCX, SLC6A3, AGAP2-AS1, LINC00968, PTX3 and SBSPON), while ITPRID1, DCST2, ETV3L, and ENSG00000261327 were down-regulated." (PMID 36647156, 2023).
neurodevelopmental disorder (7 papers, 2014 to 2022). A behavioral and cognitive disorder with onset during the developmental period that involves impaired or aberrant development of intellectual, motor, or social functions. "The SLC6A3 gene (solute carrier family 6 member 3) encodes a dopamine transporter (DAT) related to the active re-uptake of dopamine neurotransmisser—and as such, is related to some neurogenetive disorders (such as Parksons disease), neurodevelopmental disorders and memory." (PMID 30645614, 2019).
SLC6A3 also shares sentences with these, for which no sentence is quoted: Parkinsonism (207 papers); Tremor (30); neurodegenerative disease (23); Alzheimer disease (21); essential tremor (21); neuroblastoma (21); autism (20); cognitive decline (16); multiple system atrophy (15); psychosis (15); iron deficiency (14); REM sleep behavior disorder (14); Apathy (13); parkinsonian disorder (12); progressive supranuclear palsy (11); anxiety disorder (10); infection (10); vascular parkinsonism (9); brain disorder (8); cocaine abuse (8); diabetes (8); epilepsy (8); obsessive-compulsive disorder (8); corticobasal degeneration (7); cerebellar ataxia (6); Insulin resistance (6); narcolepsy (6); sleep disorder (6); coloboma (5); frontotemporal dementia (5).
A further 169 diseases each share a sentence with SLC6A3 in 5 papers or fewer.